RNU6-727P (RNA, U6 small nuclear 727, pseudogene)
Gene: Small nuclear RNA gene on chromosome 5 (87,420,341 to 87,420,447, reverse strand). Ensembl gene ENSG00000200462.
Homologues: Orthologues: chimpanzee U6 (100% identical), macaque U6 (97% identical), rabbit U6 (84% identical), dog U6 (82% identical), rat LOC120097659 (81% identical). Paralogues in human: RNU6-43P (93% identical), RNU6-1094P (91% identical), RNU6-1243P (91% identical), RNU6-1309P (91% identical), RNU6-24P (91% identical), RNU6-1091P (90% identical), RNU6-11P (90% identical), RNU6-1331P (90% identical), RNU6-238P (90% identical), RNU6-37P (90% identical), RNU6-797P (90% identical), RNU6-1011P (89% identical), and 1288 more.